GOLGA8G (golgin A8 family member G)
Synonyms: DKFZp434K052
Tractability: No criterion of Open Targets' tractability assessment is met for any kind of drug.
Gene: Protein-coding gene on chromosome 15 (28,519,611 to 28,533,014, reverse strand). Ensembl gene ENSG00000183629.
Gene Ontology:
Cellular component: cis-Golgi network; Golgi apparatus
Homologues: Orthologues: mouse Golga2 (47% identical), dog GOLGA2 (45% identical), tropical clawed frog golga2 (34% identical), zebrafish golga2 (30% identical), Drosophila melanogaster GM130 (23% identical), Caenorhabditis elegans golg-2 (20% identical), rat Golga2l1 (5% identical). Paralogues in human: GOLGA8F (98% identical), GOLGA8S (91% identical), GOLGA8M (79% identical), GOLGA8J (79% identical), GOLGA8H (79% identical), GOLGA8K (78% identical), GOLGA8T (78% identical), GOLGA8N (78% identical), GOLGA8O (78% identical), GOLGA8Q (77% identical), GOLGA8R (77% identical), GOLGA8A (71% identical), and 6 more.